RMST (rhabdomyosarcoma 2 associated transcript)
Synonyms: NCRMS; NCRNA00054; LINC00054
Gene: Long non-coding RNA gene on chromosome 12 (97,386,565 to 97,598,415, forward strand). Ensembl gene ENSG00000255794.
Diseases named in the same sentence as RMST in open-access papers:
RMST is named in the same sentence as 19 diseases in open-access papers, as found by Europe PMC text mining. Sharing a sentence is not in itself a finding about the gene and the disease. The quoted sentences say what the papers report.
triple-negative breast carcinoma (8 papers, 2019 to 2023). An invasive breast carcinoma which is negative for expression of estrogen receptor (ER), progesterone receptor (PR), and human epidermal growth factor receptor 2 (HER2). "Recent studies indicate that a trans-spliced tsRMST inhibited human embryonic stem cell differentiation, and RMST has been also implicated possessing a tumor suppressor role in triple-negative breast cancers." (PMID 31825894, 2019). "RMST has been also implicated in a tumor suppressor role in triple-negative breast cancers." (PMID 31825894, 2019). "RMST has been reported to be deregulated in a series of human cancers, to play an anti-oncogenic role in triple-negative breast cancer, and to modulate neurogenesis by interacting with SOX2." (PMID 37393309, 2023). "RMST acts as a tumor suppressor in triple-negative breast cancer (TNBC) by inducing apoptosis and inhibiting proliferation/invasion and migration." (PMID 32591022, 2020). "RMST also exerted anti-oncogenic role in triple-negative breast cancer (TNBC) since it was found downregulated in TNBC tissues, where its restoration inhibits cell proliferation, cell cycle, invasion, and migration in TNBC cells." (PMID 31963578, 2020). "In previous studies, RMST was shown to possibly inhibit cell proliferation, invasion, and migration, enhance cell apoptosis, and regulate the cell cycle to act as a tumour suppressor in triple-negative breast cancer." (PMID 31842887, 2019). "Of note, RMST was proposed as a putative regulator of NOTCH/WNT signaling pathways and a tumor suppressor lncRNA; for example, in triple-negative breast carcinoma, RMST has been shown to restrain the invasion and migration abilities." (PMID 32899940, 2020).
rhabdomyosarcoma (4 papers, 2017 to 2022). A rare aggressive malignant mesenchymal neoplasm arising from skeletal muscle. "MEG3 CRNDE, LINC00340, and RMST (rhabdomyosarcoma 2 associated transcript) is also found in various cancers." (PMID 28321286, 2017). "The remaining four DElncRNAs (MEG3, maternally expressed gene 3; RMST, rhabdomyosarcoma 2-associated transcript; HNF1A-AS1, HNF1A antisense RNA 1; and PVT1, and plasmacytoma variant translocation 1) and two DEmiRNAs (hsa-mir-429 and hsa-mir-200a) appeared to be protective." (PMID 36101743, 2022). "RMST is a 2100nt lncRNA found in the gene region of rhabdomyosarcoma, which plays an important role in the pluripotency and neural differentiation of embryonic stem cells." (PMID 35067166, 2022).
glioblastoma (3 papers, 2021 to 2024). The most malignant astrocytic tumor (WHO grade IV). "We know that RMST is required for neuronal differentiation of embryonic stem cells and that RMST knockdown in glioblastoma cells significantly decreases cell viability, proliferation, migration, and invasion and its overexpression elicits the opposite." (PMID 34744768, 2021). "Some genes that were topmost DE in glioblastoma nuclei include RMST, ID4 and PBX3." (PMID 36865335, 2023).
fibrosis (1 paper, 2023). the formation of excess fibrous connective tissue in an organ or tissue in a reparative or reactive process. "This illustrates that RMST may have a similar biological function among humans, mice, and pigs, which is also supported by the evidence that the effect of RMST knockdown on reducing cardiac fibrosis and restoring cardiac function in MI pigs is consistent with that in MI mice." (PMID 37441584, 2023).
gastric cancer (1 paper, 2024). A primary or metastatic malignant neoplasm involving the stomach. "Here, RMST was observed to regulate cellular processes in gastric cancer, with its knockdown significantly suppressing such processes." (PMID 38610003, 2024). "Overexpression of RMST significantly reduced miR-204-5p levels in gastric cancer." (PMID 38610003, 2024). "RMST levels showed strong correlation with patients’ lymph node metastasis and TNM stage and serving as a predictor of adverse prognosis RMST negatively regulated miR-204-5p, which in turn mediated the inhibitory effects of RMST knockdown on gastric cancer cell growth and metastasis." (PMID 38610003, 2024). "Additionally, silencing miR-204-5p alleviated the inhibitory effects of RMST on gastric cancer cells, suggesting that modulating miR-204-5p may be the underlying mechanism driving the tumor promoter role of RMST in gastric cancer." (PMID 38610003, 2024). "In this study, the upregulation of RMST was closely correlated with advanced TNM stage and lymph node metastasis in patients with gastric cancer, indicating its involvement in cancer progression." (PMID 38610003, 2024).
ischemic stroke (1 paper, 2019). A stroke disorder caused by obstruction of blood flow to the brain, due to thrombotic (local blood clot formation) or embolic (due to a blood clot or other material traveling from another site) event. "In addition, RMST silencing protected against ischemic injury; thus, RMST inhibition has potential for treating ischemic stroke." (PMID 30967760, 2019).
lymph node metastasis (1 paper, 2024). "The expression of RMST was significantly associated with the lymph node metastasis status (P = 0.017) and TNM stage (P = 0.021) of patients." (PMID 38610003, 2024).
Stroke (1 paper, 2026). Sudden impairment of blood flow to a part of the brain due to occlusion or rupture of an artery to the brain. "It is particularly noteworthy that LncRNA KCNQ1OT1, MALAT1, MIR17HG, and RMST are upregulated in hS3-treated healthy neuronal cultures, as these lncRNAs are known to be highly upregulated in stroke and inflammatory diseases." (PMID 41602576, 2026).
thyroid carcinomas (1 paper, 2023). "In conclusion, the data shown in this study support the involvement of RMST downregulation in the loss of differentiation and the gain of malignancy in thyroid carcinomas." (PMID 37393309, 2023).
tumor (12 papers, 2010 to 2025). "In cancer, RMST predominantly functions as a tumor suppressor, with context-dependent roles observed across different cancer types." (PMID 39201613, 2024). "Given the tumor suppressor role played by the lncRNAs MPPED2-AS1, RMST, Klhl14-AS and PAR5 in several types of cancers, where they are downregulated, we asked whether these lncRNAs could also be involved in bladder carcinogenesis." (PMID 37238229, 2023). "In another study, four lncRNAs (SNHG3, RMST, ZNF667-AS1,and COLCA1) were demonstrated to be significantly dysregulated according to the next-generation sequencing on a cohort containing 48 renal cell carcinoma paired tumor and non-tumor tissues, and further validated by qPCR." (PMID 41042421, 2025). "They demonstrated that MSC-AS1, POLR2J4, EIF3J-AS1, SERHL, RMST, and PVT1 were significantly upregulated in tumor samples compared to nontumor samples and were significantly associated with RFS." (PMID 33520012, 2020).
cancer (7 papers, 2017 to 2024). A tumor composed of atypical neoplastic, often pleomorphic cells that invade other tissues. "Thus, RMST downregulation appears correlated with the loss of the differentiated thyroid phenotype and with an increased aggressiveness of cancer samples." (PMID 37393309, 2023). "DIRC3 and RMST both were associated with the “Pathways in cancer” and “Endocytosis”." (PMID 35356464, 2022). "It is worth noting, however, that the expression of MPPED2-AS1, RMST and Klhl14-AS is distributed over a much wider range of values in cancers than in normal tissues, while PAR5 values are scattered in a similar range between cancers and controls." (PMID 37238229, 2023). "In particular, RMST was characterized as a positive regulator for DNMT3 but not DNMT1 by increasing DNMT3 mRNA stability in cancer." (PMID 36911851, 2022).
metabolic disease (1 paper, 2022). A congenital disorder (due to inherited enzyme abnormality) or acquired (due to failure of a metabolically important organ) disorder resulting from an abnormal metabolic process. "Associations with nutritional and metabolic diseases were also less important, and were mainly linked to the genes RMST, HK1, HLA-DQA1 and LAMP2." (PMID 36430729, 2022).
RMST also shares sentences with these, for which no sentence is quoted: breast carcinoma (2 papers); atherosclerosis (1); Bladder Urothelial Cancer (1); endometrial cancer (1); glioma (1); schwannoma (1); sudden cardiac arrest (1).